MIR328 (microRNA 328)
Synonyms: hsa-mir-328; MIRN328; mir-328
Gene: MicroRNA gene on chromosome 16 (67,202,321 to 67,202,395, reverse strand). Ensembl gene ENSG00000207948.
Gene Ontology:
Biological process: miRNA-mediated post-transcriptional gene silencing
Cellular component: RISC complex